TFF3 (trefoil factor 3)
Diseases named in the same sentence as TFF3 in open-access papers (continued):
Sharing a sentence is not in itself a finding about the gene and the disease.
breast carcinoma (continued). "Depletion of TFF3 in mammary carcinoma cells by siRNA concordantly decreased the angiogenic behavior of HUVEC." (PMID 26559818, 2015). "TFF3 promoted de novo angiogenesis is mediated directly on endothelial cells and indirectly by enhanced IL-8 expression in mammary carcinoma cells." (PMID 26559818, 2015). "In any case, it is clear that endothelial cells possess a functional response to TFF3 as do mammary carcinoma cells." (PMID 26559818, 2015). "There is accumulated evidence that the expression of TFF3 is positively correlated with metastasis of mammary carcinoma." (PMID 26559818, 2015). "For example, the expression of IL-8 is highly increased in tamoxifen resistance mammary carcinoma cells as TFF3 possesses a clear functional role in tamoxifen resistant mammary carcinoma." (PMID 26559818, 2015). "In summary, we have demonstrated that TFF3 functions as a promoter of angiogenesis in mammary carcinoma." (PMID 26559818, 2015). "Herein, we have shown that TFF3 secreted from mammary carcinoma cells is a functional promoter of tumor angiogenesis as demonstrated in both in vitro and in vivo xenograft models." (PMID 26559818, 2015). "Clinically, the expression of TFF3 was positively correlated with tumor vascularity in gastric and microvessel density in mammary carcinoma." (PMID 26559818, 2015). "Forced expression of TFF3 in mammary carcinoma cells has been demonstrated to promote oncogenicity, cellular invasion and resistance to apoptosis." (PMID 26559818, 2015). "We have now demonstrated herein that mammary carcinoma derived TFF3 is a potent angiogenic factor in mammary carcinoma." (PMID 26559818, 2015). "MCF-7 and T47D cells utilized herein expressed moderate levels of TFF3 and were selected as an appropriate model to study TFF3 function in ER+ mammary carcinoma cell lines." (PMID 26559818, 2015). "Forced expression of TFF3 in mammary carcinoma cells promoted proliferation, survival, invasion and in vitro tubule formation of human umbilical vein endothelial cells (HUVEC)." (PMID 26559818, 2015). "TFF3 expression in mammary carcinoma was reported to independently predict lymphovascular invasion and dissemination to lymph nodes." (PMID 26559818, 2015). "Previous studies showed that TFF3 was frequently over-expressed in breast cancer and other primary tumors." (PMID 24358147, 2013). "A xenotransplantation model in mice was utilized to determine whether TFF3 promotes the proliferation of BRCA (breast cancer) cells in vivo." (PMID 41551914, 2026). "Over the past decade, TFF3 has emerged as a promising therapeutic target due to its promotory role in cancer progression, including colorectal, hepatocellular, lung, pancreatic, prostate, cervical, endometrial, and ER+ mammary carcinomas." (PMID 39920140, 2025). "Prior studies have reported elevated TFF3 expression in breast cancer stem cells (BCSCs)." (PMID 39920140, 2025). "TFF3 is significantly upregulated in breast cancer and is sufficient to initiate tumorigenesis." (PMID 40969325, 2025). "Our data mining approach yielded 150 potential extracellularly targeted breast cancer-associated proteins starting with just 23 initial ‘seed’ markers, of which only two were known to be extracellular targeted proteins (LAMC2 and TFF3)." (PMID 36140706, 2022). "Additionally, we identified a significant association of genes involved in treatment response in breast cancer with genes producing splicing-derived neoepitopes (ERBB2, ESR1, TIMP1, ABCC3) or potentially depleted self-epitopes (AKT1, CCNE1, RET, TFF3)." (PMID 34529669, 2021). "TFF3 could promote angiogenesis in mammary carcinoma or in human umbilical vein endothelial cells via up-regulation of vascular endothelial growth factor (VEGF)." (PMID 30424721, 2018). "The use of TFF1 and TFF3 as markers in the CTCs of breast cancer patients is hopeful." (PMID 29977293, 2018). "Finally, we analyzed the results of the combined analysis of TFF1 and TFF3 in the blood of breast cancer patients." (PMID 29977293, 2018).
breast carcinoma (continued). "Furthermore, we showed that TFF3 mediates trastuzumab resistance in HER2+/ER+ breast cancer with decreased HER2 expression and signalling." (PMID 29088778, 2017). "In this study, we have analyzed whether serum TFF1, TFF2, and TFF3 can be biomarkers of breast cancer." (PMID 28687783, 2017). "In normal epithelial tissue surrounding breast cancer, 10 (21.7%) patients were positive for TFF3." (PMID 28687783, 2017). "TFF3 has previously been reported to act through STAT3 to stimulate breast cancer metastasis." (PMID 29100386, 2017). "As we observed that TFF3 expression is HER2-regulated and activates HER signalling, we went on to determine whether TFF3 modulates trastuzumab response in HER2+/ER+ breast cancer cells." (PMID 29088778, 2017). "In addition, we have previously demonstrated that TFF3 promotes metastasis and angiogenesis in mammary carcinoma." (PMID 28445151, 2017). "In addition, increased expression of TFF3 is fundamentally involved in acquired tamoxifen resistance and disease relapse in estrogen receptor positive (ER+) mammary carcinoma cells." (PMID 28445151, 2017). "Furthermore, with the presence of this cross-regulation, we have shown that TFF3 is functionally involved in mediating acquired trastuzumab resistance in HER2+/ER+ breast cancer." (PMID 29088778, 2017). "Overall, 34 out of 46 (73.9%) breast cancer was positive for TFF3." (PMID 28687783, 2017). "Thus, high TFF3 expression has been associated with favorable prognosis in ovarian cancer and with low grade in early stage breast cancer, and TFF3 seems to act as a tumor suppressor in thyroid cancer." (PMID 28930171, 2017). "It will be necessary to determine whether decreased HER2 levels and signalling can transcriptionally activate TFF3 in HER2+/ER+ breast cancer cells in general or whether this is a trastuzumab-dependent effect." (PMID 29088778, 2017). "We have analyzed serum TFF1, TFF2, and TFF3 as screening biomarkers for breast cancer." (PMID 28687783, 2017). "Furthermore, TFF3 inhibition abrogated the enhanced cancer stem cell-like behaviour in trastuzumab resistant HER2+/ER+ breast cancer cells." (PMID 29088778, 2017). "In summary, this study has demonstrated that the serum TFF1, TFF2, and TFF3 could be effective markers for breast cancer screening." (PMID 28687783, 2017). "As we know TFF3 is a soluble peptide containing trefoil domain and C-terminal dimerization domain which is not only a novel prognostic marker but also a therapeutic target in various cancers, such as mammary carcinoma, gastric cancer and prostate carcinoma." (PMID 28070169, 2017). "TFF1 and TFF3 are expressed in both breast cancer tissue and normal breast." (PMID 28687783, 2017). "Besides being an estrogen-responsive gene, TFF3 has been shown to increase ERα transcriptional activity in breast cancer, thereby promoting estrogen-independent growth and decreasing sensitivity towards anti-estrogens." (PMID 29088778, 2017). "TFF3 is found to be upregulated in and responsible for, the development and progression of several cancers including gastric cancer, hepatocellular carcinoma, prostate cancer, cervical cancer, lung adenocarcinoma and breast cancer." (PMID 29088778, 2017). "Moreover, it has been reported that while TFF3 is upregulated in tamoxifen and aromatase inhibitor resistant breast cancers, the depletion or inhibition of TFF3 resulted in re-sensitization of these resistant cells to the respective anti-estrogen." (PMID 29088778, 2017). "The loss of HER2 and upregulation of TFF3 may serve as potential biomarkers to select for trastuzumab-refractory HER2+/ER+ breast cancer patients who may benefit from therapeutic inhibition of TFF3." (PMID 29088778, 2017). "In addition, BCL-2 is found to be an important downstream mediator of TFF3-stimulated anchorage-independent growth and anti-estrogen resistance in mammary carcinoma cells." (PMID 28445151, 2017).
breast carcinoma (continued). "TFF1 and TFF3 have an estrogen responsive element, and bad prognosis of TFF1 and/or TFF3 positive breast cancer may be masked by good prognosis of ER+ breast cancer." (PMID 28687783, 2017). "Previously, we observed TFF3 expression to be associated with low HER2 levels in a mammary carcinoma patient cohort, although the difference was not statistically significant." (PMID 29088778, 2017). "Moreover, in a recent study, we observed that forced expression of TFF3 in breast cancer cells increases c-Src activation." (PMID 28445151, 2017). "Moreover, forced expression of TFF3 in mammary carcinoma and prostate cancer cells significantly increased cell proliferation, viability and survival." (PMID 27626280, 2016). "There are three clinical settings in which the measurement of TFF3 could inform the clinical management of breast cancer patients." (PMID 25900183, 2015). "TFF3 has previously been reported to promote survival of various cancer cell lineages and enhance resistance to serum deprivation, tamoxifen in mammary carcinoma cells and drug-induced apoptosis in colon carcinoma cells." (PMID 26559818, 2015). "We investigated the possibility that TFF3 might be a predictive biomarker of oestrogen responsiveness because it mediates the effects of oestrogen on breast cancer metastasis." (PMID 25900183, 2015). "TFF3 stimulated the migration of breast cancer cells in an in vitro wounding assay." (PMID 25900183, 2015). "We investigated if the predictive ability of TFF3 might be connected with an ability to mediate malign effects of oestrogen on breast cancer cell migration and invasion." (PMID 25900183, 2015). "TFF3 stimulated migration and invasion of breast cancer cells." (PMID 25900183, 2015). "Additionally, we have demonstrated herein that forced expression of TFF3 in mammary carcinoma cells promoted migration and invasion of HUVEC." (PMID 26559818, 2015). "Given that these cellular processes are also stimulated by TFF3, it is reasonable to conclude that TFF3 regulated IL-8 may cooperate together with TFF3 to promote cell proliferation, invasion and metastasis of mammary carcinoma." (PMID 26559818, 2015). "We, and numerous others, have previously reported that TFF3 is an estrogen regulated gene and is expressed predominantly in the ER+ and luminal subtype of breast cancer, and hence is also one of the genes characterizing the luminal subtype as both luminal A and luminal B are ER+." (PMID 26559818, 2015). "TFF3 has been demonstrated to promote STAT3 activity in the mammary carcinoma cells used herein." (PMID 26559818, 2015). "Therefore, TFF3 produced by mammary carcinoma cells enhances IL-8 expression in mammary carcinoma and endothelial cells." (PMID 26559818, 2015). "Interestingly, ARTN also promotes the expression of other secreted proteins, such as TFF3 which also promotes the oncogenic behaviour of mammary carcinoma cells and possesses angiogenic activity." (PMID 23185544, 2012). "Also, the luminal breast cancer-related gene TFF3 was found to be up-regulated in CTCs and lung metastasis compared to primary tumor and lymph-node metastases, and associated to an epithelial-like CTC phenotype in the experimental model and in breast cancer patients." (PMID 35216615, 2022). "Notably, TFF3 has been shown to promote oncogenic transformation of immortalized mammary epithelial cell lines, and to possess pro-proliferative, anti-apoptotic, anti-anoikis, pro-metastatic and pro-angiogenic properties in breast cancer." (PMID 29088778, 2017). "Furthermore, TFF3 has been shown to activate cSRC in MCF7 breast cancer cells, which could in turn mediate EGFR phosphorylation." (PMID 29088778, 2017). "Hence, we also examined whether TFF3 modulates the CSC-like population in trastuzumab-resistant HER2+/ER+ breast cancer cells." (PMID 29088778, 2017).
breast carcinoma (continued). "The evaluation of TFF3 expression in addition to oestrogen and progesterone receptors could identify additional breast cancer patients who might benefit from endocrine intervention and could inform the clinical management of patients with low oestrogen receptor positivity." (PMID 25900183, 2015). "Hence, TFF3 secreted from mammary carcinoma cells promoted HUVEC cell proliferation and survival." (PMID 26559818, 2015). "Hence, TFF3 is a potent angiogenic factor and functions as a promoter of de novo angiogenesis in mammary carcinoma, which may co-coordinate with the growth promoting and metastatic actions of TFF3 in mammary carcinoma to enhance tumor progression." (PMID 26559818, 2015). "Recently, several studies have reported that TFF3 promotes a CSC-like phenotype in pancreatic, colorectal, hepatocellular, lung, cervical, and ER+ mammary carcinoma." (PMID 39920140, 2025). "TFF3 and RARG were strongly expressed in breast cancer tissues, supporting their involvement in TNBC pathogenesis." (PMID 40969325, 2025). "Another implication is that four of the genes identified in this study—AGR2, AGR3, TFF3, and SCUBE2—have protein products that are secreted in the blood by breast cancer." (PMID 36836779, 2023). "Previous studies show that MGP promotes the breast cancer proliferation, SCGB2A2 and TFF3 can be viewed a valuable predictive biomarker in breast cancer." (PMID 38096269, 2023). "Interestingly, TFF3 was also found to be significantly upregulated in T cell-cold tumors of diverse tissue types, and it was in the top percentile of genes differentially expressed in T cell-cold versus T cell-hot breast cancers, which suggests its potential as an immunotherapy target." (PMID 35992833, 2022). "Recently, several studies reported that TFF3 promoted CSC-like properties in the colorectal, hepatocellular, lung, and mammary carcinoma." (PMID 35332126, 2022). "As a result of our algorithm, we identified a signature of 5 CTC-specific genes, i.e., ADPRHL1, ELF3, FCF1, TFF1 and TFF3, and explored its clinical significance according to their expression in CTC-enriched blood samples in our breast cancer case series." (PMID 35216615, 2022). "There was significant co-expression of TFF3 and AKT1 in breast carcinoma cases treated with neoadjuvant therapy (p = 0.0365) which supports the anti-apoptotic role of TFF3." (PMID 30744593, 2019). "We next examined the correlations between serum TFF1 and TFF3 levels and expression of TFF1 and TFF3 in breast cancer." (PMID 28687783, 2017). "Next, we determined HER signalling status, and the interaction between TFF3 and HER signalling in trastuzumab resistant HER2+/ER+ breast cancer cells." (PMID 29088778, 2017). "TFF3 expression was decreased by HER2 activation, and increased by inhibition of HER2 with trastuzumab in HER2+/ER+ breast cancer cells, partially in an ERα-independent manner." (PMID 29088778, 2017). "Our current findings are consistent with these observations in that HER2 transcriptionally represses TFF3, while trastuzumab inhibition of HER2 releases the transcriptional repression on TFF3 in HER2+/ER+ breast cancer cells." (PMID 29088778, 2017). "Serum TFF2 levels in breast cancer patients were significantly lower than in healthy individuals (TFF1: 1.48 ± 1.43 ng/ml, P = 0.0004, TFF2: 3.90 ± 1.90 ng/ml, P = 0.0003, TFF3: 6.96 ± 1.45 ng/ml, P = 0.0313)." (PMID 28687783, 2017). "As such, our study demonstrated that the forced expression of TFF3 increased, while the depletion or inhibition of TFF3 decreased, phosphorylation of the HER family of receptors in HER2+/ER+ breast cancer cells." (PMID 29088778, 2017). "Consistent with published literature, TFF3 has been demonstrated to increase phosphorylation of AKT and p44/42 MAPK in HER2+/ER+ breast cancer cells in this study." (PMID 29088778, 2017).
breast carcinoma (continued). "Herein, we investigated the cross-regulation between HER2 and estrogen-responsive TFF3, and the role of TFF3 in mediating trastuzumab resistance in HER2+/ER+ breast cancer." (PMID 29088778, 2017). "It is known that TFF3 induces the expressions of AR, FOXA1, HER2 and basic fibroblast growth factor (bFGF) in vitro in various cancers such as breast cancer and melanoma cells." (PMID 28070169, 2017). "As a result of the cross-regulation between TFF3 and HER2, we observed that TFF3 partially decreased trastuzumab response in HER2+/ER+ breast cancer cells." (PMID 29088778, 2017). "Herein, we demonstrated that TFF3 is transcriptionally downregulated by HER2 activation and upregulated by trastuzumab inhibition of HER2 in HER2+/ER+ breast cancer cells." (PMID 29088778, 2017). "We found that TFF3 is negatively regulated by HER2 and is employed by HER2 to maintain the appropriate level of HER signalling in HER2+/ER+ breast cancer cells." (PMID 29088778, 2017). "Our group has earlier shown that TFF3 increased STAT3 activity, which resulted in downregulation of E-cadherin, stimulated invasion and metastasis of ER+ mammary carcinomas." (PMID 29100386, 2017). "The positive rate of TFF1 and TFF3 in invasive lobular carcinoma, ductal carcinoma in situ (DCIS), and lobular carcinoma in situ (LCIS) was reported to be higher than in invasive ductal carcinoma." (PMID 28687783, 2017). "In our model of acquired trastuzumab resistance in HER2+/ER+ breast cancer, the expression of HER2 and other members of the HER family was markedly downregulated, while TFF3 was highly upregulated." (PMID 29088778, 2017). "In this report, AUC of combination of serum TFF1, TFF2, and TFF3 is 0.96 suggesting that combined testing for TFF1, TFF2, and TFF3 can provide a powerful tool for breast cancer screening." (PMID 28687783, 2017). "Serum TFF1 and TFF3 were significantly higher and serum TFF2 was significantly lower in breast cancer patients." (PMID 28687783, 2017). "And denying the tumor volume in analyzing correlation between TFF1, TFF2, and TFF3 expressions in breast cancer tissue and serum TFF1, TFF2, and TFF3 is also a limitation." (PMID 28687783, 2017). "As expected, this list contains numerous markers of breast cancer cells whose expression specificity was previously reported by other (notably ERBB3, XBP1, KRT18, IL6ST, CREB1, TFF1, TFF3)." (PMID 19104654, 2008). "While 58 (43%) cases of breast carcinoma biopsies with incomplete response or no response to neo-adjuvant therapy have shown moderate to high expression of TFF3 in pre-neoadjuvant biopsies and post neoadjuvant biopsies." (PMID 30744593, 2019). "In total 27 (85%) of breast carcinoma cases that have complete response to neoadjuvant therapy have shown either no expression or low expression of TFF3 in neoplastic cells at pre-neoadjuvant biopsies." (PMID 30744593, 2019). "Trefoil factor (TFF) peptides are family of small regulatory proteins consisting of three members, TFF1 (pS2), originally identified as an estrogen-responsive gene in the MCF-7 human breast cancer cell line, Spasmolytic polypeptide, TFF2 (SP), and intestinal trefoil factor, TFF3 (ITF)." (PMID 30744593, 2019). "As regards TFF3 mRNA, it was detected at higher levels in 46.2% of metastatic breast cancer patients as compared to 4% of nonmetastatic (p= 0.026)." (PMID 29977293, 2018). "The combined measurement of both TFF1 and TFF3 mRNA level for differentiation of metastatic from nonmetastatic breast cancer gave 57.69% sensitivity and 83.3% specificity." (PMID 29977293, 2018). "Immunohistochemically, TFF1 expression was positive in 56.5% and TFF3 was positive in 73.9% of breast cancers, while TFF2 was negative in all tumors." (PMID 28687783, 2017). "In addition, we observed that the high level of TFF3 in trastuzumab resistant HER2+/ER+ breast cancer cells maintains the activity of the remaining HER receptors, concordant with our finding that TFF3 activates HER signalling." (PMID 29088778, 2017).